WASIR2 (WASIR family lncRNA 2)
Synonyms: NCRNA00286A
Gene: Long non-coding RNA gene on chromosome 16 (22,845 to 25,191, forward strand). Ensembl gene ENSG00000231439.
Diseases named in the same sentence as WASIR2 in open-access papers:
WASIR2 is named in the same sentence as 5 diseases in open-access papers, as found by Europe PMC text mining. Sharing a sentence is not in itself a finding about the gene and the disease. The quoted sentences say what the papers report.
lung adenocarcinoma (2 papers, 2022 to 2023). A carcinoma that arises from the lung and is characterized by the presence of malignant glandular epithelial cells. "Similarly, it has been shown that WASIR2 knockdown suppressed the malignant activity of osteosarcoma cells; RPARP-AS1 and GAS5 can be used as prognostic biomarkers for lung adenocarcinoma (LUAD) and PCa, respectively." (PMID 36358967, 2022).
colon cancer (1 paper, 2023). "It was found that lncRNA WASIR2 was upregulated in colon cancer tissue and had independent prognostic significance for stage II colon cancer." (PMID 37158958, 2023).
cancer (1 paper, 2019). A tumor composed of atypical neoplastic, often pleomorphic cells that invade other tissues. "The survival analysis showed that lncRNA AF186192.1, LINC01354 and WASIR2 might act as cancer suppressor genes regulated by DNA methylation to play significant roles in predicting the prognosis of LUAD." (PMID 31558162, 2019).
WASIR2 also shares sentences with these, for which no sentence is quoted: tumor (2 papers); osteosarcoma (1).